LINC01385 (long independently transcribed non-coding RNA 1385)
Synonyms: TCONS_00009424
Gene: Long non-coding RNA gene on chromosome 5 (73,451,498 to 73,461,409, forward strand). Ensembl gene ENSG00000251604.
Diseases named in the same sentence as LINC01385 in open-access papers:
LINC01385 is named in the same sentence as 1 disease in open-access papers, as found by Europe PMC text mining. Sharing a sentence is not in itself a finding about the gene and the disease. The quoted sentences say what the papers report.
nasopharyngeal carcinoma (1 paper, 2023). A carcinoma arising from the nasopharyngeal epithelium. "High expression of LINC01385 was correlated with advanced clinical features and poor prognosis of nasopharyngeal carcinoma (NPC), and knockdown of LINC01385 inhibited the proliferation and invasion abilities of NPC cells." (PMID 37205188, 2023).